TM7SF2 (transmembrane 7 superfamily member 2)
Diseases named in the same sentence as TM7SF2 in open-access papers (continued):
Sharing a sentence is not in itself a finding about the gene and the disease.
kidney failure (1 paper, 2015). An acute or chronic condition that is characterized by the inability of the kidneys to adequately filter the blood. "Because the insufficiency of Tm7sf2 caused a reduction in LPS-induced lipid accumulation and iNOS up-regulation, we surmised that KO mice might be less prone to the kidney failure induced by the administration of LPS." (PMID 26540160, 2015). "Here, by using Tm7sf2+/+and Tm7sf2−/− mice, we investigated whether the Tm7sf2 gene, through its role in cholesterol biosynthesis under stress conditions, is involved in the renal failure induced by the administration of LPS." (PMID 26540160, 2015).
lung carcinoma (1 paper, 2025). "TM7SF2 has been identified as a critical regulator of cholesterol biosynthesis and steroid metabolism in lung cancer cells, a finding central to overcoming chemoresistance in NSCLC." (PMID 41003326, 2025). "Collectively, these findings establish TM7SF2-mediated cholesterol metabolism as a druggable vulnerability in refractory lung cancer and underscore marine-derived bromotyrosine scaffolds as promising chemical platforms for overcoming kinase inhibitor resistance." (PMID 41003326, 2025).
lymph node metastasis (1 paper, 2025). "Additionally, the significantly higher TM7SF2 expression in patients with advanced lymph node metastasis indicates that TM7SF2 overexpression may promote cancer cell invasion and metastasis." (PMID 39996914, 2025).
metastatic colorectal cancer (1 paper, 2025). "A deeper understanding of TM7SF2’s role could lead to the development of more effective treatment strategies, particularly for patients with metastatic colorectal cancer or those for whom conventional therapies are less effective." (PMID 39996914, 2025).
papilloma (1 paper, 2015). A benign epithelial neoplasm that projects above the surrounding epithelial surface and consists of villous or arborescent outgrowths of fibrovascular stroma. "By week 19, papillomas developed in Tm7sf2−/− mice were greater in size (17 ± 10 mm2 in WT vs 43.2 ± 14 mm2 in KO mice p = 0.039)." (PMID 25804527, 2015). "By week 15, 30% of Tm7sf2+/+ and 55% of Tm7sf2−/− mice showed papillomas." (PMID 25804527, 2015).
vitamin D deficiency (1 paper, 2017). A nutritional condition produced by a deficiency of VITAMIN D in the diet, insufficient production of vitamin D in the skin, inadequate absorption of vitamin D from the diet, or abnormal conversion of vitamin D to its bioactive metabolites. "Importantly, five key enzymes in the consecutive enzymatic reactions in steroid biosynthesis, including Lss, Cyp51, Tm7sf2, Nsdhl, and Hsd17b7, were downregulated, indicating a possible mechanism for vitamin D deficiency in NAFLD." (PMID 28179399, 2017).
cancer (10 papers, 2015 to 2025). A tumor composed of atypical neoplastic, often pleomorphic cells that invade other tissues. "Based on the GEPIA database, TM7SF2 gene expression in cancer was significantly associated with CPT1A (P = 8.2 × 10−11, R = 0.36)." (PMID 38693136, 2024). "Meanwhile the upregulation of TM7SF2 has been implicated in oncogenesis and cancer progression, but further studies are needed to understand this phenomenon and its role during oxidative stress challenge." (PMID 28676096, 2017). "A soft agar colony-forming assay was conducted to assess the impact of TM7SF2 downregulation on cancer cell colony formation." (PMID 39996914, 2025). "Nevertheless, the role of TM7SF2 is unclear in multiple kinds of cancers and further investigate is needed." (PMID 34667152, 2021). "Nevertheless, the role of TM7SF2 in the regulation of growth and progression among various cancers is unclear." (PMID 34667152, 2021). "TM7SF2 is a human sterol reductase with a function that remains mysterious in human cancers." (PMID 33997099, 2021). "Interactions of Beclin 1 with TM7SF2 may also have a significance in cancer-dependent autophagy." (PMID 34440098, 2021).
tumor (8 papers, 2015 to 2025). "Future studies should further investigate the functional changes and underlying mechanisms associated with reduced tumor progression following TM7SF2 suppression." (PMID 39996914, 2025). "While the mechanism by which the loss of Tm7sf2 expression promotes tumour development in the skin remains to be definitively elucidated our data offer some tantalising clues." (PMID 25804527, 2015). "The relationship between TM7SF2 expression and various factors, including age, gender, tumor size (pT stage), lymph node involvement (pN stage), metastasis, and clinical stage, was statistically analyzed." (PMID 39996914, 2025). "In vivo experiments revealed that M16 knockdown suppressed tumor growth, while TM7SF2 overexpression reversed this effect." (PMID 40860196, 2025). "IHC analysis revealed significant upregulation of TM7SF2 in CRC tissues compared to adjacent non-tumor tissues." (PMID 40860196, 2025). "We noted that the transcript levels of HMGCR, HMGCS1 and TM7SF2 were significantly higher in 231-HM cells recovered from primary tumours compared to levels in cultured cells." (PMID 39273106, 2024). "Our findings indicated that TM7SF2 plays a vital role in tumor promotion by involving in C-Raf/ERK activation." (PMID 34667152, 2021). "Immunohistochemical (IHC) staining also showed that tumor sections from nude mice that injected subcutaneously with TM7SF2-KO C33A cells expressed more apoptotic marker Cleaved caspase-3, while TM7SF2-OE C33A cells showed lower expression of Cleaved caspase-3." (PMID 34667152, 2021). "We then subjected Tm7sf2+/+ and Tm7sf2-/- mice to a classical two-stage skin carcinogenesis protocol." (PMID 25804527, 2015). "The first detectable tumour (>2 mm) appeared after 9 weeks of treatment in the null genotype and after 11 weeks in Tm7sf2+/+ mice." (PMID 25804527, 2015). "Even tumour multiplicity was higher in Tm7sf2−/− animals and this difference reached statistical significance after 15 weeks of treatment." (PMID 25804527, 2015). "Furthermore, we found that the proliferation marker PCNA was strongly upregulated in tumor sections from TM7SF2-OE nude mice group but PCNA expression was decreased in TM7SF2-KO nude mice group." (PMID 34667152, 2021). "While the target genes of this transcription factor in the skin are currently unknown, our data connect Tm7sf2 to both anti-proliferative and tumour resistance responses." (PMID 25804527, 2015). "Moreover, TM7SF2 overexpression contributed to enhancement of xenograft tumor growth in vivo." (PMID 34667152, 2021). "In the Th17 lineage, RORC (receptor) is upregulated on the tumor infiltrating CD4+ T-cells and its ligands (CYP51A1, FDFT1, HSD17B7, LBR, TM7SF2, MSMO1, NSDHL) are also upregulated on the tumor cells, implying GBM expresses ligands that induces Th17 phenotype in tumor infiltrating helper T-cell." (PMID 34012510, 2021). "In addition, IHC provided further support showing that depletion of TM7SF2 significantly decreased CPT1A protein expression, whereas upregulation of TM7SF2 significantly increased CPT1A protein expression in mouse tumor tissues compared to corresponding controls." (PMID 38693136, 2024). "However, whether TM7SF2 remodels lipid metabolism by mediating CPT1A and thus promotes tumor occurrence have not been unequivocally identified." (PMID 38693136, 2024).
skeletal dysplasia (1 paper, 2020). Any Mendelian diseases that affects growth and development of the skeleton. "TM7SF2 is a paralog of the well-characterized NET lamin B-receptor (LBR) that has been linked to the human disorders Pelger-Huet anomaly and Greenberg skeletal dysplasia." (PMID 33330474, 2020).
TM7SF2 also shares sentences with these, for which no sentence is quoted: adrenocortical tumour (1 paper); breast carcinoma (1); Diabetes (1); dyslipidemia (1); Hepatic steatosis (1); hepatocellular carcinoma (1); Hypercholesterolemia (1); laminopathy (1); liver diseases (1); melanoma (1); non-alcoholic steatohepatitis (1); renal failure (1); Sepsis (1); skin cancer (1).